CSF1 (colony stimulating factor 1)
Diseases named in the same sentence as CSF1 in open-access papers (continued):
Sharing a sentence is not in itself a finding about the gene and the disease.
tumor (continued). "CSF-1 positive staining mainly appeared in the cytoplasm of tumor cells." (PMID 25886010, 2015). "Macrophages are among the first immune cells to infiltrate the tumor lesions and then influence the tumor progression/invasion via secretion of several growth factors, cytokines or chemokines, including colony stimulating factor 1 (CSF-1), vascular epithelial growth factor (VEGF) and CCL2." (PMID 25623427, 2015). "Moreover, in a mouse model of pancreatic ductal adenocarcinoma, blockade of CSF-1/CSF-1R signaling results in macrophage reprograming to support anti-tumor immune function and modestly delays tumor growth." (PMID 26500653, 2015). "Tumor cells in turn express CSF-1 and can further stimulate and recruit macrophages." (PMID 26010447, 2015). "Our finding that Vav1 affects CSF1 expression and secretion and that the tumor microenvironment might also be involved in such a process prompted us to ask whether CSF1 is critical for Vav1 dependent lung tumor growth in vitro." (PMID 25313137, 2014). "Moreover, irradiation stimulates tumor cells to produce higher levels of CSF-1 resulting in the enhanced infiltration of pro-angiogenic myeloid cells into the tumor site." (PMID 24634660, 2014). "The current review article describes the functional relationship between tumor-associated macrophages (TAM) as key cellular contributors to cancer malignancy on the one hand and macrophage-colony-stimulating factor (M-CSF or CSF-1) as an important molecular contributor on the other." (PMID 25339957, 2014). "Metastatic tumor cells express both secreted and surface forms of CSF-1." (PMID 25147739, 2014). "Our study reveals that Vav1 and CSF1 influence the activity of each other and are engaged in an autocrine mechanism that could enhance tumor growth." (PMID 25313137, 2014). "Interestingly, the ability of macrophages to migrate to tumor sites involves the expression of specific proteins, e.g., colony stimulating factor-1 (CSF-1) receptor and integrin." (PMID 24116086, 2013). "CSF-1, also known as macrophage-colony stimulating factor (M-CSF), is the main regulator of the proliferation, differentiation, survival, and chemotaxis of monocytes/macrophages in tumor-bearing mice." (PMID 24314323, 2013). "Tumor-associated microglia notably break into the tumor mass in response to chemo-attractive cytokines released by the tumor it-self such as monocyte chemotactic protein-3 (MCP-3), colony-stimulating factor 1 (CSF-1) and granulocyte-colony stimulatory factor (G-CSF)." (PMID 24202333, 2013). "Ex vivo incubation of isolated tumor cells with EGCG inhibited the CSF-1 and CCL-2 expression." (PMID 24044575, 2013). "A special role was highlighted for CSF-1, which is secreted from tumor cells and helps recruit macrophages and sustain them in the tumoral microenvironment, and to EGF, which is secreted from the infiltrating macrophages and serves to induce tumor cell migration and invasion." (PMID 23785333, 2013). "The treatment of cell with CSF-1 mimicked the presence of macrophages in the tumor microenvironment, as our previous findings have demonstrated that the presence of macrophages in the tumor microenvironment increases CSF-1R expression in cancer cells." (PMID 23561040, 2013). "Moreover, TAMs are necessary for metastasis, and their ability to secrete EGF together with the ability of tumor cells to secrete M-CSF/CSF-1 stimulate mutual migration in both cell types." (PMID 23785333, 2013). "In addition to tumor cells, vascular ECs in the perivascular microenvironment can produce CSF1 and promote the functional polarization of M2-like macrophages that accelerate angiogenesis and tumor growth." (PMID 24314323, 2013). "CCL5 and CSF-1 are examples of monocyte-recruiting cytokines released by tumor cells." (PMID 22992343, 2012).
tumor (continued). "As would be expected, TAMs possess M2-like traits; Tumour cells and the tumour microenvironment release a variety of factors that facilitate this, including IL-4, IL-6, IL-10, PGE2, TGF-β1 and CSF-1, expressed by tumour cells, as well as IL-10, PGE2 and MMP-7 expressed by TAMs." (PMID 22005011, 2011). "In this respect, activation of CSF-1R by its ligand is likely to occur in tumor cells in which CSF-1R and CSF-1 are co-expressed (i.e. autocrine activation), or when CSF-1R is stimulated by CSF-1 released by cancer associated fibroblasts (i.e. paracrine activation)." (PMID 22096574, 2011). "Tumor-derived CSF1 overexpression is a common finding in many types of human neoplasms." (PMID 20981142, 2010). "To assess the representativeness of the PVNS/TGCT renal subcapsular xenografts, we examined side by side the harvested graft tissues and their corresponding primary tumor specimens, comparing their histomorphological features, CSF1 translocation status, and CSF1 protein expression patterns." (PMID 20981142, 2010). "Harvested grafts maintained characteristic features of the original tumors with respect to tumor morphology, CSF1 translocation status, CSF1, and macrophage CD163 expression, making this the first PVNS model of practical use for preclinical therapeutic investigation." (PMID 20981142, 2010). "Furthermore, the study of invasion, intravasation and metastasis using both methods has shown the involvement of a paracrine loop between macrophages and tumor cells that secrete EGF or colony stimulating factor-1 (CSF1), respectively." (PMID 21108830, 2010). "The CSF-1 pathway is required for macrophage differentiation and survival, yet previous work suggests the CSF-1 pathway may also drive tumor cell progression." (PMID 21049007, 2010). "Combined with our result showing downregulation of CSF-1 expression by hypoxic tumor cells, we hypothesize that high oxygen tension at the tumor periphery and low oxygen tension at the tumor core create a chemoattractant gradient of CSF-1." (PMID 19696929, 2009). "Based on our findings and the work of others we propose a hypothetical model in which normoxic invasive tumor cells release CSF-1 into the extracellular environment creating a chemokine gradient that immobilizes monocytes/macrophages to the invasive tumor edge." (PMID 19696929, 2009). "CSF-1 release by tumor cells is also thought to play a role." (PMID 19906309, 2009). "This suggests that a positive feedback loop may exists between resident TAMs and tumor cells to maintain a locally high concentration of CSF-1." (PMID 19696929, 2009). "While preliminary, this mechanism could direct macrophages to the tumor edge where they further amplify CSF-1 concentrations through positive feedback mechanisms." (PMID 19696929, 2009). "Importantly, our gene array findings indicate that RAW 264.7 macrophage-derived chemokines upregulate CSF-1 production by CT26 tumor cells." (PMID 19696929, 2009). "Engagement of αvβ3 integrin with bone ECM proteins may induce production of an osteoclast-stimulating factor, such as RANKL or colony stimulating factor 1, by tumor cells or by bone marrow cells." (PMID 16608535, 2006). "Colony stimulating factor 1 (CSF-1), a cytokine commonly produced by tumours, triggers monocyte migration and blocking CSF-1 or its receptor has been shown to suppress macrophage infiltration and to reduce tumour growth." (PMID 16832418, 2006). "Macrophages also migrate to the tumor site, where tumor cells are responsible for a switch in macrophage phenotype, favoring a pro-invasive and immunosuppressive M2 state via the release of immunosuppressive factors, such as CSF-1, CCL2, IL-4, IL-6, IL-10, and TGF-β." (PMID 41373591, 2025). "In addition, the colony-stimulating factor-1 (CSF1)/CSF1 receptor (CSF1R) axis plays a multifaceted role in the tumor microenvironment (TME), with particular relevance to its function in the survival and activation of tumor-associated macrophages." (PMID 40052125, 2025).
tumor (continued). "In addition, therapeutic drugs targeting CSF‐1 secretion in melanoma have been shown to reduce the expansion of the monocyte–myeloid‐derived suppressor cells subset and macrophage conversion, reprogram regulatory myeloid cells, and reduce tumor progression." (PMID 40717900, 2025). "However, the signal provided by tumor cell-derived CSF-1 that triggers the secretion of VEGF-A by the TMEM doorway macrophage, the most critical step for TMEM doorway opening, has remained unknown, until now." (PMID 40646332, 2025). "Similarly, to establish that CSF-1 secreted by tumor cells specifically is responsible for the increased trans-endothelial migration, and not the other TMEM doorway cells present in the iTEM assay, we knocked down CSF-1 in MDA-MB-231 cells using siRNA and used these tumor cells in the iTEM assay." (PMID 40646332, 2025). "Furthermore, CSF-1 depletion results in a large reduction in macrophage density, which delays tumor progression and significantly inhibits metastasis, as demonstrated by tumor transplantation models." (PMID 38655133, 2024). "In addition to regulating neutrophils, LY500307 reduced the recruitment of CSF-1 receptor-positive myeloid-derived suppressor cells (MDSC) to the tumor microenvironment while also increasing CD8+ cytotoxic T cells by decreasing the production of CSF-1 by tumor cells." (PMID 39175529, 2024). "Consistently, CSF-1– CSF-1 receptor (CSF-1R) axis blockade or macrophage recruitment blockade via C-C chemokine receptor type 2 (CCR2)-inhibition could restore immune response against tumor in cancer models." (PMID 38426089, 2024). "Moreover, we have proposed the notion that anti‐CSF‐1/CSF‐1R targeting M2 macrophages, tumor vaccines or cytokine therapies targeting bystander T cells might be effective for HRP tumors." (PMID 39136172, 2024). "In addition to fibroblasts, tumor cells can also secrete CSF1, suggesting that it may play a pro-tumorigenic role." (PMID 39416792, 2024). "Finally, we also wanted to understand whether the drugs would influence CSF-1 or CSF-1R expression in tumor cells." (PMID 38303927, 2024). "Therefore, targeting the CSF1/CSF1R signaling pathway may represent a promising anti-tumor strategy in the future." (PMID 39416792, 2024). "Moreover, when looking at the broader cellular context, lymphocytes from clusters 7 and 28 expressed significant TGFB1 and tumor clusters 3, 8, and 14 expressed substantial CSF1, which promote immunosuppressive and pro-inflammatory properties in macrophages, respectively." (PMID 36966348, 2023). "Cxcl2, Ccl2, Ccl3, and Ccl8 can act as chemoattractants for myeloid cell recruitment in tumors, while Csf1, Csf2, and Csf3 are central to controlling the recruitment, proliferation, and differentiation of immunosuppressive myeloid cells, including macrophages and neutrophils in the tumor." (PMID 37138326, 2023). "Moreover, pretreating A2780 cells with NHWD-870 reduced CSF-1 production in tumor cells." (PMID 37675155, 2023). "CSF1 can recruit and transform macrophages to the M2 phenotype to promote immune escape in a tumor microenvironment, and can increase invasion of EVT, suggesting that it may possibly participate in the establishment of maternal-fetal immune tolerance in early pregnancy." (PMID 37854606, 2023). "Moreover, CCR2 and CSF1R surface proteins of MφNP may interact with CCL2 and CSF1, respectively, which are known for recruiting monocytes and macrophages into the tumor tissue." (PMID 38111068, 2023). "The CCL2 and CSF1 metastatic sites might draw MφNPs into the metastatic tumor regions." (PMID 38111068, 2023). "In addition to stimulating the accumulation of macrophages in tumors, CSF1 can also promote the survival and differentiation of monocytes into macrophages, increasing the infiltration of macrophages in tumor tissues, thereby promoting tumor metastasis and angiogenesis." (PMID 36377508, 2023).
tumor (continued). "Thus, Vav1 could influence tumor growth and the tumor’s microenvironment via CSF-1 in an autocrine/paracrine mechanism." (PMID 35326399, 2022). "In the same way, CCL2 produced by tumor cells and CSF1 produced by tumor-associated fibroblasts contribute to the generation of M2-like macrophages, and CXCL1 production by tumor cells has been linked to increased myeloid cell populations and decreased tumor infiltration of cytotoxic CD8+ T cells." (PMID 36408139, 2022). "Thus, a local environment with high CSF-1 concentration may favor tumor cells to invade and metastasize." (PMID 36555673, 2022). "The immune cells that reside in the tumor microenvironment include lymphocytes, macrophages, and polymorphonucleocytes, many of which migrate into the tumor through the generation of tumoral chemo-attractants such as CSF-1, IL-3, and VEGF and chemokines such as CCL-2." (PMID 35326557, 2022). "However, secretion and proteolytic release of certain cytokines and growth factors, such as colony stimulating factor-1 (CSF-1) and interleukin-4 (IL-4), by the tumor cells educate TAMs toward a tumor-promoting phenotype, sharing many features of alternatively activated M2 macrophages." (PMID 35998057, 2022). "Thus, the rate of tumor progression is reduced substantially in CSF-1-knockout mice." (PMID 35326399, 2022). "As a feedback loop, tumour cells secrete CXCL16 and CSF1 (colony-stimulating factor 1), both of which depend on the transcriptional activity of HIFs, leading to the recruitment of MSCs and macrophages to primary tumours and mediating the metastasis of tumour cells to lymph nodes and lungs." (PMID 35869057, 2022). "However, in tumor immune microenvironment, Macrophages M1 transform into M2 activated by interleukin-4, -10, -13 (IL-4, IL-10, and IL-13), colony-stimulating factor-1 (CSF-1), and tumor growth factor β (TGF-β)." (PMID 35432538, 2022). "Treatment targeting the receptor or its ligand, CSF-1R/CSF-1, has been found to improve T cell responses; further, combining CSF-1R inhibition with checkpoint blockades or adoptive T cell transfer therapy resulted in an improved anti-tumor T cell activity and tumor regression." (PMID 35628647, 2022). "Overexpression of CSF-1, the major lineage regulator for macrophages, is associated with poor prognosis in breast, ovarian, endometrial, prostate, hepatocellular, and colorectal cancer, as the intra-tumoral presence of CSF1R+ macrophages correlates with poor survival in various tumor types." (PMID 35327359, 2022). "In fact, depletion of macrophages indiscriminately by drugs targeting CSF1 or CSF1R will cause substantial toxicity to normal tissues, instead, targeting downstream pro-tumor molecule mediated by CSF1, such as CXCL7, may be a better candidate for future drug development." (PMID 34789744, 2021). "However, the expression of CSF1 was significantly higher in p16INK4A positive tumor cells." (PMID 33643790, 2021). "In addition to fibroblasts, CSF-1 can be secreted by tumor cells, suggesting that it may play a pro-tumorigenic role." (PMID 34729112, 2021). "In preclinical models, blockade of CSF-1/CSF-1R signaling inhibited recruitment of bone marrow myeloid cells to the tumor during chemotherapy and induced type I interferon response, thereby reversing chemoresistance and sensitizing tumor cells to chemotherapy 1-3." (PMID 33537102, 2021). "This was driven by radiation-induced expression and secretion of CSF-1 that, when blocked with small molecule inhibitors of the CSF-1 receptor (CSF-1R), markedly reduced the expansion of myeloid cells and enhanced the response of the irradiated tumour to radiation." (PMID 34299373, 2021). "Noninvasive imaging of myeloid cells that illuminates the effects of CSF-1/CSF-1R blockade on the bone marrow, spleen, and tumor may improve understanding of the engagement of CSF-1/CSF-1R pathway inhibitors in patients, thereby facilitating the development of optimal combination strategies." (PMID 33537102, 2021).
tumor (continued). "Thus, CSF1 limits granulocyte recruitment to the tumor tissue." (PMID 33670714, 2021). "We next asked whether CSF1 promotes tumor formation through TAMs in A2780 orthotopic tumor model." (PMID 32286255, 2020). "Moreover, tumor-derived CSF-1 and IL-4 synergistically induce M2-type polarization of macrophages." (PMID 33224886, 2020). "We then asked whether NHWD-870 affected CSF1 expression in tumor cells." (PMID 32286255, 2020). "Treatments targeting the receptor or its ligand CSF-1R/CSF-1 has been found to improve T-cell responses and combining CSF-1R inhibition with checkpoint blockades or adoptive T-cell transfer therapy resulted in improved anti-tumour T-cell activity and tumour regression." (PMID 32121014, 2020). "Interestingly, CSF1/CSFR1 blockade achieved up to 85% tumor regression in a murine model when combined with PD1/CTLA4 inhibitors and gemcitabine, improved tumor regression in this murine model as well as increased effector CD8+ and CD4+ TIL infiltration and activity." (PMID 32823814, 2020). "However, tumor infiltrating MDSCs polarized toward TAM by CSF-1 and HIF-1α." (PMID 33062602, 2020). "It has been demonstrated that irradiated tumors showed enhanced tumor-associated macrophage (TAM) infiltration, possibly attributed to the upregulation of chemoattractant stromal cell-derived factor 1 (SDF-1) and colony-stimulating factor 1 (CSF-1) as well as C-X-C chemokine receptor type 4." (PMID 32723363, 2020). "However, in a myeloid cell-rich tumor model, CSF1 but not IL34 was required for tumor-associated macrophage accumulation and immune homeostasis." (PMID 31552020, 2019). "Since CSF-1 is needed to polarize the TAMs into the immunosuppressive M2 phenotype at the first stage of their generation, the blockade of CSF-1 could decrease the TAMs at the tumor sites, leading to induction of immunoreactive effector T cells at the tumor site." (PMID 31514399, 2019). "Moreover, CSF-1 has also been reported to induce angiogenic activity via recruitment of macrophages, which secrete growth factors, proangiogenic cytokines, and matrix metalloproteases (MMPs) to regulate tumor cell invasion." (PMID 31565097, 2019). "Macrophages can secrete a variety of cytokines capable of paracrine signaling and potentially affecting tumor biology; one study suggested that CSF-1 production with macrophage infiltration may promote neovascularization, and angiogenesis plays an important role in tumor growth." (PMID 30999901, 2019). "In addition, Csf-1 −/− BRAF transgenic mice displayed a reduction in tumor growth." (PMID 31412566, 2019). "The authors also indicated that CSF1/CSF1R blockade might reduce PD-L1 expression in tumor cells." (PMID 31521128, 2019). "These considerations suggest the intriguing possibility that macrophage detection of elevated CSF-1 levels, in this case driven by dense concentrations of CSF-1-producing tumor cells, could be considered a sensing mechanism for local disturbances in homeostasis." (PMID 29757143, 2018). "This may be important in the context of the aging microenvironment, as tumor-derived CSF-1 could circulate to stimulate macrophage population expansion in various tissues and also help to chemoattract such macrophages to the tumor, further driving macrophage-mediated tumor growth in the elderly." (PMID 30459812, 2018). "Recent studies have revealed that CSF-1 signals are critical for the survival, tumor infiltration and differentiation with immunosuppressive phenotypes of macrophages, and CSF-1 inhibitors have emerged as potent antitumor agents to prevent tumor growth and metastasis." (PMID 28686632, 2017). "This action of CSF-1 could enhance the metastatic potential of tumor." (PMID 28567162, 2017).